ECRG4 (ECRG4 augurin precursor)
Diseases named in the same sentence as ECRG4 in open-access papers (continued):
Sharing a sentence is not in itself a finding about the gene and the disease.
tumor (32 papers, 2009 to 2025). "Esophageal cancer-related gene 4 (Ecrg4) encodes a hormone-like peptide that is believed to be involved in a variety of physiological phenomena, including tumour suppression." (PMID 29511297, 2018). "One new candidate signal is augurin, a newly recognized 14 kDa protein that is encoded by esophageal cancer related gene-4 (Ecrg4), a putative tumor suppressor gene whose presence and function in normal tissues remains unexplored and enigmatic." (PMID 21349154, 2011). "For example, Esophageal Cancer Related Gene-4 (Ecrg4) is a tumor suppressor gene that encodes a hormone-like peptide called augurin that is present in large concentrations in CP epithelia (CPe)." (PMID 21935431, 2011). "Remarkably, ECRG4 is downregulated in the vast majority of cancer types compared to the corresponding normal tissues, displaying the characteristics of a tumor suppressor gene." (PMID 37041625, 2023). "Esophageal cancer-related gene-4 (ECRG4), a 148-amino acid propertied and new tumor suppressor, is initially cloned from the normal esophageal epithelium." (PMID 36910669, 2023). "ECRG4 has several functions, including tumor suppression, heart rhythm regulation, cardiac homeostasis maintenance, and involvement in the aging process." (PMID 36910669, 2023). "In colorectal and gastric cancers, UBR5 was found to accelerate tumor growth by destabilizing the tumor suppressors ECRG4 and GKN1 following their ubiquitination." (PMID 33777788, 2021). "ITIH5 and ECRG4 have been previously identified as putative class II tumor suppressor genes, which are epigenetically silenced in various tumor entities." (PMID 32046186, 2020). "In this independent cohort, a close association of both ECRG4 and ITIH5 with increased tumor size (pTa vs. pT1-4) and age at diagnosis was determined by Fisher’s exact test." (PMID 32046186, 2020). "Overexpression of ECRG4 was able to inhibit the proliferation, migration, and invasion of several tumor cells." (PMID 30918105, 2019). "Here, we observed that ECRG4 mRNA levels were frequently much lower in tumor tissues (82.4%) than in their normal counterparts." (PMID 30918105, 2019). "Since then, ECRG4 has been shown to participate in many physiological phenomena, including tumour suppression, cell senescence, central nervous system homeostasis, Alzheimer’s disease, and immune responses." (PMID 29511297, 2018). "The growth rate and metastasis of the tumor cells in xenografts were suppressed following the overexpression of ECRG4 in nude mice." (PMID 23833667, 2013). "The possibility that Ecrg4 over-expression inhibits NSPC activation in the SVZ after injury, is consistent with the predicted inhibitory effects of Ecrg4 gene expression on other cell types, particularly tumor cells." (PMID 21349154, 2011). "The Ecrg4 gene is a candidate tumor suppressor gene that has gained significant attention because of the inverse association of gene expression with the growth and progression of epithelial cancers." (PMID 21935431, 2011). "In tumor cell models and in specimens derived from human biopsies, Ecrg4 gene expression has been related to the production of a putative secreted tumor suppressor." (PMID 21349154, 2011). "Of note, the pattern of expression was observed homogeneously through all the data sets, and more than 90% of tumor samples showed ECRG4 underexpression as compared to NB in each data set and in the pooled data set." (PMID 22110708, 2011). "Data from aCGH were available for 247 of the 353 tumor samples from our institution, allowing us to analyze the ECRG4 locus at 2q12.2." (PMID 22110708, 2011). "Decreased Ecrg4 gene expression is correlated with the transition from benign to malignant tumor cell growth and the degree of Ecrg4 gene suppression corresponds to aggressive growth." (PMID 21349154, 2011). "Here, we report on a further molecular and functional characterization of ECRG4 as a potential tumor suppressor gene in different types of cancer." (PMID 20017917, 2009).
tumor (continued). "To determine if ECRG4 promoter methylation is correlated to gene expression, we analyzed relative expression levels of ECRG4 by semiquantitative RT-PCR in eight tumor and nine normal tissues." (PMID 20017917, 2009). "We found significantly lower expression of ECRG4 in tumor tissues as compared to control tissue (BI = 0.33 vs. BI = 1.44; unpaired t-test; p = 0.0018)." (PMID 20017917, 2009). "As a tumor suppressor, ECRG4 is downregulated in cancers due to promoter methylation, and its immune activation and tumor inhibition functions may be attributed to its TLR4-targeted internalization domain." (PMID 38833013, 2024). "ECRG4 not only has a tumor suppressor effect but also cytokine-like functions." (PMID 36910669, 2023). "Unlike most tumor suppressor genes, which are usually membrane or intracellular proteins, ECRG4 is a 148 amino acid propeptide that is covalently linked to the amino end on cell surfaces." (PMID 36910669, 2023). "As a tumor suppressor gene, full-length ECRG4 may act to block the growth of stromal cells in the normal ME, maintaining homeostasis of the mucosa." (PMID 36092940, 2022). "ECRG4 may act as a tumor suppressor, inhibiting proliferation and migration, inducing G0/G1 phase arrest and apoptosis via the mitochondrial apoptotic pathway." (PMID 30918105, 2019). "We observed lower ECRG4 mRNA expression in 82.4% of tumor tissues (14/17)." (PMID 30918105, 2019). "If functional analyses confirm this TSG role, restoring ECRG4 expression in the tumor may represent a promising therapeutic approach." (PMID 22110708, 2011). "We analyzed the panel of tumor cell lines for expression of ECRG4 using RT-PCR." (PMID 20017917, 2009). "Taken together, the high incidence of AF in tumor patients may be related to ECRG4 expression." (PMID 36910669, 2023). "It was first speculated that Ecrg4 might be a tumor suppressor gene, due to its decreased expression in esophageal cell carcinomas, while still detectable in the normal esophageal epithelia surrounding the tumor." (PMID 36227903, 2022). "Taken together, these data support a hypothesis that Ecrg4 plays a role in coordinating the inflammatory and proliferative response to infection of mucosal epithelium suggesting a possible mechanism for its putative anti-tumor activity." (PMID 23626679, 2013). "ECRG4 expression was significantly (t-test) associated with age inferior to 50 years, early clinical stage, small pathological tumor size, absence of axillary lymph node involvement, low tumor grade, and histological type (being the highest in lobular type and the lowest in medullary type)." (PMID 22110708, 2011). "Furthermore, ECRG4 overexpression in ESCC cells inhibited tumor cells growth and invasion." (PMID 21288367, 2011). "Together these results suggest that ECRG4 might play a suppressive role in tumor pathogenesis." (PMID 20598162, 2010). "In addition, serum exosomes contain ECRG4 could suppress tumor growth." (PMID 36915206, 2023). "ECRG4 and LDOC1 were selected for further analysis based on their putative function as tumor suppressor genes in other cancer types." (PMID 23185447, 2012). "Together, these findings suggest that Ecrg4 acts as an inflammatory cytokine that regulates many physiological processes, rather than a traditional tumour suppressor." (PMID 29511297, 2018). "The patients whose tumor expressed higher levels of ECRG4 mRNA survived longer and without relapse than those with lower levels." (PMID 22110708, 2011). "In the course of a DNA methylation screening in sarcoma cells using a methylated CpG island amplification coupled with representational difference analysis (MCA-RDA) approach, we identified the ECRG4 gene at 2q12.2 as a gene showing aberrant promoter methylation in tumor but not in normal cells." (PMID 20017917, 2009).
cancer (30 papers, 2009 to 2025). A tumor composed of atypical neoplastic, often pleomorphic cells that invade other tissues. "It has been shown that the ECRG4 promoter undergoes aberrant methylation which causes extinction of its expression in a variety of different human cancers, such as esophageal and colorectal cancer, malignant glioma, breast and prostate cancer." (PMID 37041625, 2023). "Interestingly, ECRG4 expression has been shown to be regulated by hypermethylation of the promoter, which leads to loss of its expression in various cancers." (PMID 39509414, 2024). "Because previous studies demonstrated that Ecrg4 gene expression is associated with epithelial cells, cancers and barriers, we tested the possibility that Ecrg4 could regulate the inflammatory response to infection." (PMID 23626679, 2013). "A study has reported that ECRG4 is downregulated and acts as a tumor suppressor gene in most types of cancers." (PMID 32922434, 2020). "Herein, we showed that esophageal cancer-related gene-4 (ECRG4), which is downregulated in BCa tissues and cell lines, has a positive correlation with osteoglycin (OGN)." (PMID 32922434, 2020). "Mao and colleagues have reported that serum exosomes contain higher levels of ECRG4 mRNA in healthy individuals than in their cancer counterparts, thus showing that exosomal ECRG4 mRNA can be used for cancer detection." (PMID 33396739, 2020). "To date, many studies have focused on the upstream epigenetic regulation of ECRG4 and the promoter region of ECRG4, which is frequently hypermethylated in cancers, including BCa." (PMID 32922434, 2020). "Recent studies have validated that ECRG4 induces apoptosis in several cancers through the regulation of Bax and Bcl-2, and through the activation of caspase-3, which cleaves PARP protein." (PMID 30918105, 2019). "We recently identified a candidate gene called Esophageal cancer related gene-4 (Ecrg4) that we proposed plays a sentinel function to monitor set points of homeostasis." (PMID 23626679, 2013). "Although numerous studies have focused on the effects of ECRG4 in other cancers using the clinical and in vitro levels, studies on animals are rare." (PMID 23833667, 2013). "Recent studies on a novel gene, ECRG4, in other types of carcinomas have attracted attention to its potential role in SCCHN." (PMID 23833667, 2013). "We revealed for the first time that ECRG4 interacted directly with ECRG1 to inhibit cancer cell proliferation and induce cell cycle G1 phase block in ESCC." (PMID 21288367, 2011). "The fact that the Ecrg4 gene is down-regulated by hyper-methylation in many cancers suggests that its epigenetic control plays a role in the transformation of normal cells to cancer." (PMID 21349154, 2011). "Although Ecrg4 gene expression is well described as down-regulated in cancer and inversely correlated with cell proliferation, there is little known regarding its fate and distribution in the CNS." (PMID 21349154, 2011). "These investigators then recognized that a gene that was originally discovered in 1998 and termed esophageal cancer related gene-4 (Ecrg4) had the features of a neuropeptide within its primary sequence, but no known biological function." (PMID 21349154, 2011). "We analyzed different cancer cells for ECRG4 promoter methylation by COBRA and bisulfite sequencing." (PMID 20017917, 2009). "As epigenetic regulation of the ECRG4 promoter regulates its expression in certain cancers, this mechanism may also regulate its expression in other physiologic states or diseases, such as T2DM." (PMID 39509414, 2024). "Moreover, ECRG4 serves as an inhibitory upstream regulator of the NF-κB pathway, while the latter is persistently activated in cancer stem cells across various malignancies, participating in several crucial biological processes of cancer stem cells." (PMID 39724112, 2024). "Meanwhile, promoter methylation determines ECRG4 expression status, and its aberration could help detect early cancer and predict severity." (PMID 36910669, 2023).
cancer (continued). "Decreased concentrations of ECRG4 in body fluids may indicate cancer development, suggesting that ECRG4 may be a biomarker for predicting cancer occurrence." (PMID 36910669, 2023). "To further explore the downstream mechanism of ECRG4 in BCa cells, we examined whether ECRG4 regulates the NF-κB signaling pathway, which has been reported to play an important role in several types of cancers." (PMID 32922434, 2020). "Nevertheless, to our knowledge this is the first report to show that Ecrg4 is involved in the pathogenesis of AF, which may shed new light on a long-held mystery that why the incidence of AF is higher in cancer patients." (PMID 28578429, 2017). "In light of the down-regulation of Ecrg4 and high incidence of AF in cancer patients, we hypothesize that Ecrg4 may play an important role in the pathogenesis of AF." (PMID 28578429, 2017). "Another new candidate gene is the esophageal cancer-related gene 4 (ECRG4/C2ORF40)." (PMID 24452533, 2014). "In the present study, ECRG4 decreased the expression of cyclin A but not cyclin E, indicating that cyclin A may play a key role in ECRG4-induced cancer cell arrest at the G0/G1 cell cycle phase." (PMID 23833667, 2013). "ECRG4 was underexpressed in 94.3% of cancers when compared to NB." (PMID 22110708, 2011). "ECRG4 is silenced via promoter hypermethylation in different types of human cancer cells." (PMID 20017917, 2009). "We found a high frequency of ECRG4 promoter methylation in various cancer cell lines." (PMID 20017917, 2009). "Other Studies have found that ECRG4 can directly interact with ECRG1 to up-regulate the expression of p21, induce G1 phase arrest of cell cycle, and inhibit the proliferation of cancer cells." (PMID 36910669, 2023). "Our DNA-methylation-based predictors selected CpG sites and CGIs related to genes previously found individually involved in cancer development and with transcriptional activity regulated by methylation (e.g. MBTPS2, YY2, ECRG4, IKZF1)." (PMID 31708973, 2019). "The present study showed that ECRG4 was able to suppress SCCHN cell invasion and migration, implicating its potential involvement in cancer metastasis." (PMID 23833667, 2013). "ECRG4 interacts directly with ECRG1 to upregulate p21 protein expression, induce cell cycle G1 phase block and inhibit cancer cells proliferation in ESCC." (PMID 21288367, 2011). "Moreover, cell growth curves also demonstrated that ECRG4 and ECRG1 co-transfection significantly slowed down cancer cells growth by MTT assay (P < 0.01)." (PMID 21288367, 2011). "This suggests that the biological functions of ECRG4 are not unique to a specific cancer type, but likely common among multiple cancers." (PMID 20598162, 2010).
infection (5 papers, 2013 to 2024). The state of being infected such as from the introduction of a foreign agent such as serum, vaccine, antigenic substance or organism. "In our mouse model, loss of ECRG4 expression impairs the early recruitment of neutrophils to cutaneous infection, resulting in more severe infection and bacterial proliferation." (PMID 39509414, 2024). "The results here add to a growing body of evidence that Ecrg4 gene expression is linked to the inflammation, infection and the injury response." (PMID 23626679, 2013). "We first established that the pre-injection of ADEcrg4 onto the mucosal bed in vivo, two days before NTHi infection circumvented the loss of Ecrg4 protein expression which is normally observed 48 hrs after infection." (PMID 23626679, 2013). "Understanding this mechanism would not only support the use of ECRG4 expression as a marker for infection and chronic wound risk in T2DM patients, but also provide a target for restoring ECRG4 expression and, thus, restoring neutrophil responses to decrease these risks." (PMID 39509414, 2024). "Given the importance of this neutrophil response, we evaluated whether the ECRG4 KO mouse had deficient neutrophil recruitment that might be responsible for the observed worse infection and bacterial dissemination." (PMID 39509414, 2024). "Further elucidation of this pathway may enable the use of ECRG4 expression to identify patients at increased risk of diabetic complications, such as severe infections and chronic wounds, as well as identify novel therapeutic targets for preventing these devastating complications." (PMID 39509414, 2024). "Given the dramatic increase in bacterial burden early in the infection in ECRG4 KO mice, we evaluated mice for systemic dissemination from the cutaneous infection site." (PMID 39509414, 2024). "Here, we find that ECRG4 KO mice have deficient neutrophil recruitment to cutaneous infection with MRSA, with more severe infection and dissemination of bacteria." (PMID 39509414, 2024). "Using flow cytometry to immunophenotype cells at the site of infection, we observed that the ECRG4 KO mice had a 50% decrease in neutrophil recruitment at 24 hours (P<0.0001)." (PMID 39509414, 2024). "Time course experiments comparing ECRG4 KO mice to wild type (WT) controls demonstrated that ECRG4 KO mice rapidly developed much larger lesions after infection." (PMID 39509414, 2024). "Enumeration of bacteria in the spleen and lung at 24 hours after infection demonstrated increased MRSA in the ECRG4 KO mouse, indicating that these mice were unable to contain the cutaneous infection, resulting in systemic spread." (PMID 39509414, 2024). "Based on the findings reported here, and prior studies, we propose a mechanism whereby ECRG4 expression regulates neutrophil adhesion molecule expression to modulate the recruitment of neutrophils to sites of injury and infection." (PMID 39509414, 2024). "ECRG4 KO mice developed worse infections with higher local bacterial burden and increased dissemination, which was associated with decreased early neutrophil recruitment." (PMID 39509414, 2024). "On the contrary, we found that the ECRG4 KO mouse infection had increased expression of IL1β (P = 0.0053), IL-6 (P = 0.047) and TNFα (P = 0.024), with a trend towards increased CXCL1." (PMID 39509414, 2024). "Previous studies have determined that increased CD11b expression and activation can impair neutrophil recruitment, thus providing a potential mechanism for the observed delay in ECRG4 KO mouse neutrophil response to infection." (PMID 39509414, 2024). "This deficit in neutrophil recruitment relative to the WT control mice narrowed by 72 hours, demonstrating a trend of 20% fewer neutrophils in the ECRG4 KO infection." (PMID 39509414, 2024). "Similar to the findings in our transcriptional analysis, we found increased TNFα (P = 0.028) and CXCL1 (P = 0.0056) in the ECRG4 KO mouse infection, as well as a trend towards increased CXCL2, IL1β, and IL6." (PMID 39509414, 2024).